INS (insulin)
Diseases named in the same sentence as INS in open-access papers (continued):
Sharing a sentence is not in itself a finding about the gene and the disease.
liver fibrosis (continued). "The antihypertensive hydralazine ameliorated HFC-induced hepatic fibrosis by lowering blood pressure and improving insulin resistance." (PMID 33315911, 2020). "Telmisartan is a potential treatment for NAFLD due to its ability to improve insulin sensitivity and decrease hepatic fat accumulation via modulation of PPARγ, and to suppress hepatic fibrosis by blocking angiotensin II receptors." (PMID 30850637, 2019). "In summary, we demonstrated that a high fat-sucrose diet induced serum lipid disorder and promoted NAFL progression to NASH and to liver fibrosis in an SD rat model likely through initiating insulin resistance and oxidative stress." (PMID 28820447, 2017). "These facts demonstrate that the hepatic fibrosis markers were related to glucose and insulin metabolism indicators as well." (PMID 26966436, 2016). "As such, drugs that can improve insulin sensitivity have a key role in the prognostication and therapeutic management of this disease, potentially reversing even advanced liver damage and hepatic fibrosis, improving long-term clinical outcomes." (PMID 27314342, 2016). "At 12 mo, hepatic fibrosis, indexes of inflammation, oxidative stress, and insulin signaling were measured by histology, Western blot, ELISA, and reverse transcriptase–polymerase chain reaction." (PMID 26718412, 2016). "A higher proportion of individuals classified as at high probability of liver fibrosis were treated with insulin (P = 0.01)." (PMID 24520400, 2014). "In particular, the insulin levels at 120 minutes were remarkably higher in the patients with advanced hepatic fibrosis (F0 versus F2, P<0.05; F0 versus F3, P<0.01; F1 versus F2, P<0.01; F1 versus F3, P<0.01)." (PMID 24223115, 2013). "ITGA7, important for insulin and glucose metabolism, Taylor (2018) showed hypermethylation, as did PLXND1, a therapeutic target in liver fibrosis and associated with adipocyte lipolysis, further linking these epigenetic changes to the metabolic disruptions observed due to prenatal-BPA treatment." (PMID 40914344, 2025). "In addition, 112 cases had missing data for non-invasive liver fibrosis assessment, and 64 individuals with missing insulin or CRP measurements were excluded, leading to the final sample of 10985 participants." (PMID 40642596, 2025). "Mice fed a diet high in fat with liver-specific TGFβ deletion compared with wildtype controls had significantly improved glucose tolerance and insulin sensitivity, reduced liver weights, decreased hepatic triglyceride levels, and less liver fibrosis than controls." (PMID 40985048, 2025). "Notably, the interleukin-6 (IL-6) cytokine family plays a complex role in the onset and development of MAFLD, primarily through the modulation of lipid metabolism, insulin resistance, inflammatory responses, and liver fibrosis." (PMID 40969371, 2025). "When parameters of glucose metabolism were studied, we found that higher stages of fibrosis were associated with higher glycemia, insulin, and HOMA-IR values before and after treatment and an improvement in liver fibrosis in patients with lower baseline values of insulin and HOMA-IR." (PMID 38543737, 2024). "Moreover, in mouse models, genetic ablation of DPP4 resulted in improved insulin sensitivity and liver function, while gemigliptin alleviated both liver fibrosis and mitochondrial dysfunction." (PMID 37938366, 2024). "We found that SR1664 did not improve insulin sensitivity, but effectively reduced liver fibrosis, without causing weight gain." (PMID 37886997, 2023). "The vulnerability of liver fibrosis in diabetic patients can attribute to insulin abnormalities." (PMID 37817864, 2023). "Studies revealed that estrogen may improve insulin sensitivity, lower liver de novo lipogenesis, reduce triglyceride accumulation, and ameliorate liver fibrosis and inflammation." (PMID 36120457, 2022). "Therefore, current therapeutic treatment for liver fibrosis focuses on reducing insulin resistance and improving insulin sensitivity." (PMID 35893894, 2022).
liver fibrosis (continued). "Consistent with the results of previous animal studies, the investigation of the cell insulin signaling pathway suggested that the H-L + HFD-induced liver fibrosis was mediated by gut microbiota through disruption of the gut barrier TLR4/MYD88 and liver IRS1/Akt/mTOR signaling pathways." (PMID 36204709, 2022). "After adjusting for gender, age, eGFR, HbA1c, T2DM (y/n), stages of NAFLD (1/2/3), and liver fibrosis (y/n), it was found that HepFe (p = 0.020), serum ferritin (p = 0.040), fasting insulin (p = 0.049), and platelets (p = 0.009) were significantly associated with mean UACR (R2 = 0.370; p = 0.007)." (PMID 34300354, 2021). "Triglycerides and hepatic fibrosis are associated with HCV-specific alteration of adiponectin levels, and adiponectin may affect insulin sensitivity through triglycerides during HCV infection." (PMID 34380427, 2021). "In addition, MI supplementation was effective in decreasing hepatic fibrosis and improving insulin sensitivity, as observed by histological analysis, as well as a reduction in fibrotic gene expression (Col1α1) and improved Akt activation, respectively." (PMID 34684533, 2021). "In addition, on a tissue scale, Ang II was associated with increased insulin resistance through oxidative stress, leading to hepatic fibrosis and cirrhosis, provoking an impairment of insulin signaling." (PMID 34359936, 2021). "No significant changes were observed in other efficacy assessments, which included change from baseline in liver fibrosis; proportion of participants with transaminases returning to normal range or with a reduction greater than 50%; and improvement of insulin resistance." (PMID 31536511, 2019). "Furthermore, insulin stimulates the secretion of matrix proteins and other precursors of hepatic fibrosis by hepatic stellate cells." (PMID 28831144, 2017). "Insulin stimulates hepatic stellate cell proliferation and collagen synthesis in vitro and therefore, by extension, exogenous insulin therapy could promote liver fibrosis in vivo." (PMID 26454513, 2016). "Since approximately 50% of portal insulin is cleared by the liver during first-past transit, liver fibrosis might lead to impaired hepatic clearance of insulin and, consequently, it could affect HOMA-IR values." (PMID 25159899, 2014). "Therefore, the insulin levels at 120 minutes were remarkably higher in the patients with advanced hepatic fibrosis (F0 versus F2, P<0.05; F0 versus F3, P<0.01; F1 versus F2, P<0.01; F1 versus F3, P<0.01), as previously reported." (PMID 24223115, 2013). "However, it remains poorly understood whether STING pathway dysregulation in NK cells alters their insulin responsiveness and how this might influence NK cell functionality across stages of liver fibrosis." (PMID 40643462, 2025). "However, our data showed that acute depletion of SLC25A47 by ~50% sufficiently restricted gluconeogenesis and enhanced insulin tolerance in adult mice without causing liver fibrosis and mitochondrial dysfunction." (PMID 36812201, 2023). "Thus, hPDI may prevent NAFLD and liver fibrosis partly through its anti-inflammatory or anti-insulin resistance property." (PMID 36235752, 2022). "Therefore, we searched and screened the latest relevant studies in the PubMeb database to elucidate the link between microbial-derived exosomes and the pathogenesis of MAFLD, mainly in terms of insulin resistance, intestinal barrier, inflammatory response, lipid metabolism, and liver fibrosis." (PMID 35634340, 2022). "Advanced liver fibrosis may impair insulin clearance, resulting in elevated serum insulin levels." (PMID 35095765, 2021). "The pathophysiological mechanisms behind the association of liver fibrosis in NAFLD with cardiovascular disease are still incompletely understood and may involve other pathways besides insulin resistance, such as oxidative stress, inflammation, and gut microbiota." (PMID 34560854, 2021).
liver fibrosis (continued). "Moreover, during the transition from NAFL to NASH, chemokines recruit immune cells and infiltrate into the liver and adipose tissue, such as GR1+ monocytes, which play a role in pro-inflammation, systemic insulin resistance, and pro-liver fibrosis by producing inducible nitric oxide synthase." (PMID 33042108, 2020). "Finally, we assessed the induction of liver fibrosis by treatment with insulin and/or hCG." (PMID 29719598, 2018). "However, external insulin could increase the levels of circulating insulin and aggravate liver fibrosis." (PMID 28831144, 2017). "In conclusion, the convergence of insulin and STING signaling pathways offers a promising therapeutic avenue to restore NK cell function and counteract liver fibrosis in MASH." (PMID 40643462, 2025). "Interestingly, significant associations were observed between the changes in HbA1c and the changes in the APRI or FIB-4 index in our study, suggesting that enhanced insulin action may be a common mechanism in improving glycemic control and preventing the development of liver fibrosis." (PMID 38790963, 2024). "The disease progression rate of viral hepatisis-related liver fibrosis, cirrhosis and HCC is related to host factors such as age, gender, ethanol intake, intrahepatic fat deposition and insulin resistance." (PMID 38926648, 2024). "The beneficial effects of hepatokines include 1) improvement of insulin sensitivity (FGF21); 2) prevention of liver fibrosis (FGF21, HMGB1, PST, AHSG and SERPINF1) and 3) reduction of inflammation and lipid accumulation (FGF21, HMGB1 and LECT2)." (PMID 36267567, 2022). "In liver fibrosis, nutrients and growth factors related to hepatocytes, such as hepatocyte growth factor (HGF)/epidermal growth factor (EGF) and insulin, can promote proliferation and repair." (PMID 36005144, 2022). "The results of a phase II clinical trial (NCT00501592) showed that Obeticholic Acid significantly improved insulin sensitivity in patients with T2DM complicated with NAFLD, significantly improved hepatic fibrosis, and liver enzymology indexes (p < 0.05)." (PMID 35770089, 2022). "Improve of insulin sensitivity; Prevention of HSC and liver fibrosis; Reduction of inflammation and lipid accumulation." (PMID 36267567, 2022). "Hence the increased levels of GIP, adipsin and insulin as well as of leptin, that augments insulin signal transduction, are mainly correlated not only between them but also with the decreased levels of ghrelin that has been indicated as marker of the liver fibrosis progression." (PMID 22745767, 2012). "Fifthly, our analysis solely focused on the impact of efruxifermin on liver fibrosis, while its effects on other aspects, such as glycemic control, insulin sensitivity, lipid metabolism, and weight changes, were not evaluated." (PMID 40520164, 2025). "But microbial therapies could not ameliorate body mass index (BMI), energy, carbohydrate, fat intake, fasting blood sugar, HbA1c, insulin, high-sensitivity C-reactive protein (hs-CRP), and hepatic fibrosis of patients with NAFLD." (PMID 36386939, 2022). "Differently from what reported in terms of potential benefit of vitamin D supplementation on glucose–insulin profile, evidence of efficacy on liver fibrosis and inflammation is still lacking." (PMID 33126575, 2020). "Subjects with advanced liver fibrosis had higher levels of palmitic, stearic and oleic acid and total monounsaturated fatty acid (MUFA) and insulin (p < 0.05), and lower levels of elongase very long chain fatty acids protein-6 and the delta-5-desaturase enzymatic activity (p < 0.05)." (PMID 30380656, 2018). "Despite the significant fatty changes, insulin-resistant OLETF rats with ordinary diet did not demonstrate liver fibrosis." (PMID 22710359, 2012).
liver fibrosis (continued). "Additionally, a significant improved in the ratio of F0-1 hepatic fibrosis degree, TG, HDL-C and LDL-C were noted in the 5:2 IF diet group after 12-week treatment (p < 0.05), however, lower FBS, fasting insulin and hs-CRP were noted in the daily calorie restriction eating group (p < 0.05)." (PMID 39229586, 2024). "Alternatively, the observed association between higher FIB-4 index and a development of decreased insulin secretion may not be via liver fibrosis per se." (PMID 32978491, 2020). "Furthermore, an analog of GLB reduces hepatic ATZ accumulation and hepatic fibrosis in a mouse model in vivo without affecting blood glucose or insulin levels." (PMID 30673724, 2019). "Increased KLF6 expression augments enhanced collagen 1 and TGFß1 expression to result in liver fibrosis, and overexpression of KLF2 induces expression of the fatty acid translocator CD36 whereas KLF15 plays an essential role in ER stress-mediated insulin resistance in the liver." (PMID 29296203, 2017). "Comparing baseline metabolic/cellular parameters of those who improved liver fibrosis with those who did not, we found increased values of HDL and platelet counts and decreased values of insulin and HOMA-IR for the first ones." (PMID 38543737, 2024). "Though we cannot calculate HFS since we had not tested participants’ serum insulin levels, it would have been better to add HFS to our analysis to more firmly exclude those with liver fibrosis." (PMID 34064337, 2021). "To summarize, the 4 months exposure to MF diet resulted in elevated insulin and IHTG levels, but did not induce the progression of NALFD to liver fibrosis and injury." (PMID 29266667, 2018). "Even if ISI is a better marker of insulin sensitivity as compared with fasting insulin and HOMA-IR, this evidence had no practical implication as far as the prediction of liver fibrosis is concerned." (PMID 19409076, 2009).
Hypoinsulinemia (196 papers, 2009 to 2026). A decreased concentration of insulin in the blood. "While insulin acutely augments thermogenesis in humans, partial knockout of the insulin gene in mice, resulting in chronic hypoinsulinemia, was associated with an increase in EE." (PMID 40931394, 2025). "Work in our laboratory has revealed that administration of streptozotocin (STZ), a drug that causes hypoinsulinemia by destroying insulin-producing β-cells, enhances conditioned place preference (CPP) and intravenous self-administration (IVSA)." (PMID 38389818, 2023). "Little information is known about the relationship between T1DM and AD, despite the fact that hypoinsulinemia causes a comparable impairment in insulin signalling." (PMID 35802659, 2022). "In pancreatic β cells, this stress was associated with β cell loss, hypoinsulinemia, and glucose intolerance, probably as a consequence of impaired insulin maturation." (PMID 34950970, 2021). "A single high-dose injection of TCDD in mice caused hypoinsulinemia in vivo for up to 6 weeks and reduced glucose-stimulated insulin secretion in islets ex vivo." (PMID 35295132, 2021). "Berry consumption also showed glucose-lowering and insulin sensitivity improvements, which are closely associated with hypoinsulinemia, insulin signaling activation (in adipose and skeletal muscles), the adiponectin-AMPK pathway, and GLP-1 upregulation." (PMID 32825710, 2020). "Hypoinsulinemia causes insulin-deficient diabetes, and the hormonal actions of insulin are necessary for the life of complex organisms." (PMID 32819363, 2020). "Such strategies exploiting organism-wide paradigms to establish causality between hypoinsulinemia and CNS neuronal death are based on the misconception that intracerebral insulin is solely provided from the circulation, itself supplied by the pancreas." (PMID 31787891, 2019). "The high rate of glucose in the amniotic fluid can prolonged the fetuses β-pancreatic cells stimulation, causing a pancreatic insulin depletion and hypoinsulinemia." (PMID 31717560, 2019). "The increased injury size can be effectively rescued by insulin administration, suggesting that the cause of the increased injury size is due to hypoinsulinemia." (PMID 27034963, 2016). "The fasting-associated downregulation in basal insulin signaling in muscle is likely due to the hypoinsulinemia observed in late-fasted animals." (PMID 23997935, 2013). "In both the streptozotocin (STZ) model, where hypoinsulinemia is chemically induced, and in the Ins2Akita model, which develops it spontaneously due to a mutation in the insulin gene, we observed early induction of the secreted glycoprotein gene leucine-rich α-2-glycoprotein 1 (Lrg1)." (PMID 41124286, 2025). "Insulin acts to drive fetal growth, which raises the possibility that fetal hypoinsulinemia may underlie a mechanism promoting FGR at high altitude." (PMID 38694168, 2024). "Change in gene expression may be responsible for these processes that may be associated with hypoinsulinemia and impaired insulin signaling pathway." (PMID 37217800, 2023). "Loss of this signaling through PACAP deficiency may explain the reports of hypoinsulinemia, decreased adiposity, lower body weight, and increased insulin sensitivity in PACAP-null transgenic mice." (PMID 37900572, 2023). "Plasma insulin data are limited; however, high serum PCB levels are associated with fasting hypoinsulinemia and decreased plasma insulin levels during a glucose challenge and negatively correlated with HOMA-β, suggesting a link between PCB exposure and impaired β-cell function." (PMID 35156417, 2022). "More severe hypoinsulinemia of the insulin variant of C43G15 is neonatal diabetes." (PMID 36028536, 2022). "Increased insulin sensitivity was associated with hypoinsulinemia in mouse models and humans." (PMID 33920473, 2021).